INS (insulin)
Diseases named in the same sentence as INS in open-access papers (continued):
Sharing a sentence is not in itself a finding about the gene and the disease.
Insulin resistance (continued). "HOMA–IR is a more accurate tool for the assessment of insulin sensitivity than fasting plasma insulin since it assesses the relationship between the functioning of β-cells and insulin resistance." (PMID 34572220, 2021). "Usually, an increased insulin exocytosis secondary to peripheric insulin resistance maintains the glycometabolic stability." (PMID 34512170, 2021). "The activation of AMPK in rodents with insulin resistance or T2D increases skeletal muscle glucose uptake via an insulin-independent mechanism." (PMID 34796169, 2021). "In this study, Bla.C treatment significantly improved the homeostatic model evaluation of glucose, insulin, and insulin resistance (HOMA-IR) indices and diabetic blood markers such as HbA1c in T2DM mice." (PMID 34836432, 2021). "This brilliant model is able to reproduce skeletal muscle insulin resistance, occurring in patients with T2D, in a culture dish, opening novel unexpected perspectives to explore the mechanisms of insulin resistance in peripheral tissues." (PMID 34502235, 2021). "Insulin resistance is a common pathophysiological consequence of obesity in which body cells are unable to raise a potent physiological response to insulin." (PMID 34106350, 2021). "Our study also shows that insulin and insulin resistance (HOMA-IR) levels decreased in the S, TP, and TS groups, compared to their baseline levels with the greatest improvement in the TS group." (PMID 34579020, 2021). "Results from randomized trials on the effect of vitamin D and/or calcium supplementation on insulin resistance show improvement of insulin action with supplementation." (PMID 33786167, 2021). "These mice were protected from high-fat diet-induced development of insulin resistance, as their blood glucose levels dropped lower than in wild-type mice following insulin injection." (PMID 33923452, 2021). "Plasma fasting blood glucose level, plasma insulin level, and homeostasis model assessment of insulin resistance (HOMA-IR) in diabetic rats after 4 weeks of treatments." (PMID 33996978, 2021). "Increased secretion of insulin by β-cells decreases hepatic autophagy and promotes insulin resistance in hepatocytes." (PMID 34141709, 2021). "Insulin resistance occurs due to a decrease in the metabolic response of insulin-responsive cells to insulin or, at a systemic level, an impaired/lower response to circulating insulin by blood glucose levels." (PMID 34831299, 2021). "Particularly, a greater portion of pregnant women develop insulin resistance, generally resulting in insulin overproduction to decrease glucose levels in the blood." (PMID 34070701, 2021). "So far, the liver CEACAM1 knockout mice provide an in vivo proof of the key role of impaired hepatic insulin clearance and hyperinsulinemia in the pathogenesis of secondary hepatic insulin resistance." (PMID 33477364, 2021). "Since insulin resistance and decreased Glut-4 levels in adipocyte tissue are characteristic, the development of insulin-sensitizing agents against T2DM is an important current research topic." (PMID 34133443, 2021). "Both of them are implicated in the regulation of various processes in the body, including insulin sensitivity and protection against insulin resistance." (PMID 35087866, 2021). "In the results of the study, TCDD exposure resulted in significant increase in insulin and HOMA-IR index indicating the occurrence of insulin resistance or insulin sensitivity decreased in rats." (PMID 34948750, 2021). "The repair of liver leads to the recovery of glucose and lipid metabolism, thereby alleviating insulin resistance, restoring insulin sensitivity, promoting islet regeneration, and restoring insulin secretion." (PMID 34722505, 2021). "In children and adolescents, endothelial dysfunction assessed as brachial artery FMD was inversely related to age, total and abdominal obesity, blood pressure, fasting insulin and glucose, and homeostatic model assessment-insulin resistance (HOMA-IR)." (PMID 34578869, 2021).
Insulin resistance (continued). "It has been reported that arginine and its metabolites promote insulin secretion and improve insulin resistance in humans." (PMID 34419103, 2021). "T2DM is mainly characterized by a progressive decline in insulin action (insulin resistance), followed by the inability of beta cells to compensate for insulin resistance (pancreatic beta cell dysfunction)." (PMID 34603025, 2021). "As a result, hepatic insulin extraction decreases, leading to metabolic dysregulation and increased insulin resistance." (PMID 34354748, 2021). "Insulin resistance reduces the inhibitory effect of insulin on lipolysis thus increasing the production of FFAs." (PMID 34094026, 2021). "Adiponectin was reported helpful to improve insulin sensitivity and correct disturbances in whole-body glucose homeostasis induced by a high-fat diet, but leptin increases insulin resistance under a high-fat diet." (PMID 33672704, 2021). "For instance, in hyperglycaemia and insulin resistance, insulin has growth promoting and mitogenic effects on cells." (PMID 33924591, 2021). "The aim of this study is to describe the role played by insulin in the CNS, in both healthy people and those with pathologies such as insulin resistance and Alzheimer’s disease." (PMID 34576151, 2021). "Insulin, the main antagonist of adrenergic signaling, is an anti-lipolytic hormone; insulin resistance thus can lead to further mobilization of lipid from AT in dairy cows." (PMID 34045558, 2021). "The plant extract decreased insulin resistance and increased insulin sensitivity in diabetic mice in another study." (PMID 33572627, 2021). "The evaluation of fasting glucose and insulin levels indicated the presence of insulin resistance, as insulinemia was found to be very high, in agreement with other authors evaluating CGL patients." (PMID 33411809, 2021). "For example, GLUT4 is a protein required for insulin-mediated glucose translocation in adipocytes and contributes to insulin resistance in PCOS41." (PMID 34453106, 2021). "From the second trimester, a progressive decrease in insulin sensitivity, called insulin resistance, begins, mainly in the adipose tissue, skeletal muscle and liver." (PMID 34502370, 2021). "Insulin resistance is a reduced sensitivity of body tissues to insulin, which is one of the earliest and most significant metabolic defects in T2DM." (PMID 34523794, 2021). "Insulin resistance is defined as a process in which normal or elevated insulin levels produce a reduced biological response characterized by impaired sensitivity to insulin-mediated glucose disposal." (PMID 34769018, 2021). "Visceral adipose tissue is a vital insulin responsive organ and has been confirmed to be positively correlated with insulin resistance." (PMID 34917687, 2021). "Peripheral insulin resistance mainly occurs in adipose tissue and muscles, whereby glucose uptake and utilization mediated by insulin are disrupted, and there is an increased decomposition of adipose tissue." (PMID 34950104, 2021). "Insufficient insulin secretion due to β-cell dysfunction and increased insulin resistance leads to hyperglycemia during pregnancy and GDM." (PMID 34684381, 2021). "Experimental studies in rodents demonstrated that chronic IH, per se, is responsible for systemic insulin resistance and alterations in tissue‐specific insulin signaling pathway (i.e., liver, adipose tissue and muscle)." (PMID 33682327, 2021). "Although hyperinsulinemia and a long-term insulin exposure have been shown to exacerbate glutamate excitotoxicity through inducing insulin resistance, in contrast, a short-term insulin treatment protects neurons against glutamate excitotoxicity." (PMID 33810179, 2021). "As in our previous papers, we demonstrate that the improvement in glycaemia is accompanied by an amelioration of fasting and postprandial insulin resistance, also reflected by increased hepatic insulin clearance, and a reduced level of liver fat markers." (PMID 34254189, 2021).
Insulin resistance (continued). "Viral-induced interferon-gamma secretion has been demonstrated to increase muscular insulin resistance and circulating insulin levels, which, in turn, increases the cluster of differentiation 8 cytotoxic T-cell (CD8 + T-cell) responses." (PMID 34441802, 2021). "HRT significantly decreased fasting insulin and homeostasis model assessment of insulin resistance in perimenopausal users, and fasting plasma glucose levels in postmenopausal users with prior menstrual disorders, compared with baseline." (PMID 34130678, 2021). "Accumulating evidence suggests a link between bodily iron excess and features of insulin resistance and the metabolic syndrome presenting as elevated triglycerides, low-density lipoprotein cholesterol, insulin, HOMA-IR and hypertension." (PMID 34063273, 2021). "Insulin resistance is a result of altered peripheral insulin signaling; glucose uptake is almost half that and insulin resistance is increased in GDM pregnancy compared to a physiological pregnancy." (PMID 34299269, 2021). "As a result, hyperuricemia can inhibit insulin signaling, induce insulin resistance and accelerate the process of atherosclerosis." (PMID 34335617, 2021). "Our results verify the positive and dose-dependent effect of N. sativa seed in improving insulin resistance and serum level changes of insulin in PCOS rats." (PMID 33842824, 2021). "Because Asians have lower insulin secretion capacity, they are susceptible to T2DM under increased insulin resistance states, such as aging and elevated inflammation." (PMID 34834527, 2021). "Chronic treatment with niacin induces insulin resistance through its downregulatory effect on genes involved in the insulin signaling pathway." (PMID 34575946, 2021). "In the setting of obesity-provoked insulin resistance, β-cell proliferation is a compensatory response to the increased demand of insulin." (PMID 34949756, 2021). "Within 10 years of the first use of insulin, it emerged that it did not have the same glucose-lowering effect in all patients, and the notion of insulin insensitivity or insulin resistance (IR) was born." (PMID 34841432, 2021). "CSRP3 knockout mice fed a high-fat diet had reduced insulin resistance and glucose tolerance, increased skeletal muscle inflammation, and impaired insulin signaling." (PMID 33677919, 2021). "In this model, there are both moderate impairment in insulin secretion and insulin resistance, which is a characteristic feature of T2DM." (PMID 33277985, 2021). "With use of the validated cut-off Rd < 37.3 μmol·kg−1min−1 for peripheral insulin resistance, we categorized our cohort into insulin resistant subjects n = 76 (71%) and insulin sensitive subjects n = 31 (29%)." (PMID 34444866, 2021). "Our findings suggest eGDR to be a suitable indicator of a prothrombotic profile, and superior to BMI and insulin requirements which are classical surrogates of insulin resistance." (PMID 33730349, 2021). "In the present study, DHEA-induced mice showed dramatically enhanced fast glucose level, fast insulin level and HOMA-IR index, indicating that DHEA treatment caused insulin resistance in the mice." (PMID 34637688, 2021). "As highlighted earlier, increased insulin resistance due to visceral adiposity tissue can disrupt the balance, resulting in minimised insulin-production ability in East Asians." (PMID 34822452, 2021). "The toxic lipid species (ceramide and diacyl glycerol) generated secondary to ectopic lipid accumulation are proposed to eventually inhibit insulin signalling, leading to insulin resistance." (PMID 33923531, 2021). "LJE also causes a significant decrease in circulating levels of glucose and insulin with the alleviation of insulin resistance." (PMID 34441028, 2021). "The impairment of systemic glucose metabolism is related to increased insulin resistance and insufficient insulin secretion." (PMID 33494481, 2021).
Insulin resistance (continued). "MNX mice were significantly leaner, had lower leptin levels, and were more insulin sensitive, with lower modified Homeostatic Model Assessment of Insulin Resistance (mHOMA-IR) values and enhanced insulin action when compared with their control counterparts." (PMID 34370595, 2021). "We found that the MCS ÷ FSD group had significantly higher insulin levels and higher insulin resistance compared to the controls." (PMID 34886380, 2021). "Previous studies showed that caffeine can lower insulin sensitivity and increase insulin resistance and glucose concentration." (PMID 34836231, 2021). "Regarding disorders of insulin homeostasis, converging evidence has shown that insulin resistance or consequent hyperinsulinemia is related to poor cognitive performance." (PMID 34966358, 2021). "It is worthy to note that the discrepancy in insulin secretion and insulin resistance between different races, Asians appear to worse in early phase insulin secretion than Caucasians." (PMID 33490287, 2021). "Overproduction of FFA has been directly tied with deficient insulin release by pancreatic β-cells, and inhibits insulin-stimulated glucose uptake in myocytes and hepatocytes, leading to the development of insulin resistance and type 2 diabetes." (PMID 34576943, 2021). "In combination with decreased insulin secretion by islet β-cells, the pathological condition of insulin resistance is established." (PMID 33802371, 2021). "More specifically, high insulin/high glucose (HI/HG) treatment for 24 h provoked insulin resistance and impaired autophagy flux, both of which were relieved upon re-activation of autophagy and mitigation of ER stress by rapamycin treatment." (PMID 34336862, 2021). "The decrease in glucose levels in the face of reduced plasma insulin levels indicates improved insulin sensitivity, and the expression of human AdipoR1 in skeletal muscle indeed reduced insulin resistance index in mice on a high-fat diet." (PMID 33420419, 2021). "Afamin correlated positively with hepatic lipids, fatty liver index and liver damage markers; with parameters of adiposity (waist circumference, %body fat, adipocyte diameter) and insulin resistance (fasting insulin, C-peptide, HOMA-IR; p<0.001 all)." (PMID 34603196, 2021). "Adipose tissue plays a key role in the pathogenesis of DM, evidenced by data demonstrating that selective enhancement of adipose tissue insulin sensitivity ameliorates systemic insulin resistance in murine obesity." (PMID 34462518, 2021). "Fourteen doses of H-Exo resulted in further impairments in insulin sensitivity, as mice showed insulin resistance at all time points after insulin injection (14-dose panel)." (PMID 33431899, 2021). "E3 ubiquitin ligases play pivotal roles in the process of insulin resistance and directly degrades the insulin receptor, insulin receptor substrate, and other key insulin signaling molecules via the ubiquitin-proteasome system (UPS)." (PMID 34603025, 2021). "Increased sphingolipids can induce insulin resistance by interfering with signal transduction of insulin signaling pathway and promoting cell apoptosis." (PMID 34194524, 2021). "Insulin resistance is related to the adipocyte hormones (leptin and adiponectin) that mediate insulin-sensitizing effects through the activation of adenosine monophosphate dependent kinase (AMPK), PPARγ, and some other signaling pathways." (PMID 34805244, 2021). "Upon WTD intervention, only female Cyp2c70−/− mice displayed lower fasting glucose and insulin levels and, hence, improved homeostatic model assessment-insulin resistance compared with controls." (PMID 34626589, 2021). "Fatty acid metabolites, proinflammatory cytokines and cellular stress which destruct the insulin signaling pathway and exacerbate insulin resistance and hyperglycemia in T2DM." (PMID 34003397, 2021).
Insulin resistance (continued). "The HOMA-IR index was remarkably decreased in the MET group and INS group compared with the DM group, indicating that the treatment of metformin and insulin significantly improved the insulin resistance of diabetic rats." (PMID 35046817, 2021). "There is convincing evidence that ameliorating insulin resistance and hence reducing circulating insulin levels leads to the improvement of hormonal imbalance and resumption of ovulation in PCOS subjects." (PMID 34551795, 2021). "It is well-characterized that high fat diet (HFD) provokes insulin resistance, increasing the demand for insulin production and secretion by β-cells, resulting in higher insulinemia." (PMID 33483593, 2021). "While fasting glycemia was slightly but not significantly reduced in CE-dams, we found that both fasting insulinemia and the HOMA-IR insulin resistance index to be significantly decreased, indicating an improvement of insulin sensitivity in CE-dams." (PMID 34812123, 2021). "In patients with insulin resistance, the effect of insulin is suppressed, leading to constant glucose output from the liver." (PMID 34950104, 2021). "Its levels commonly increase in obesity and DM, and it impairs insulin signaling and induces insulin resistance, while blocking it increases glucose uptake and insulin sensitivity." (PMID 34660808, 2021). "HFD would cause insulin resistance, and STZ, a most common diabetogenic agent, is particularly toxic to islet β‐cells, reducing the release of insulin and then elevating the blood glucose level." (PMID 33841817, 2021). "Animal studies have also demonstrated the importance of pulsatile insulin delivery in the development of insulin resistance." (PMID 34360563, 2021). "Insulin signalling is disrupted at several levels during insulin resistance, resulting in decreased glucose absorption in insulin-sensitive peripheral tissues." (PMID 35655910, 2021). "Combined with previous reports, a high level of insulin promoted the initiation of inflammation, and insulin resistance was aggravated by the inflammatory environment." (PMID 33743811, 2021). "Any defect in the PI3K/Akt/AS160 signaling will eventually reduce the glucose uptake in insulin-sensitive tissues and lead to insulin resistance." (PMID 34445300, 2021). "Furthermore, insulin sensitivity correlated with cardiovascular risk factors, including pulse wave velocity, even when adjusting for the degree of obesity, suggesting that insulin resistance, augmented by excess weight, is the underlying factor contributing to cardiovascular complications." (PMID 33828529, 2021). "It was reported that GH administration is followed by insulin resistance and relatively sustained hyperglycemia, probably because of the GH lipolytic effect that inhibits insulin-mediated glucose uptake, especially in the muscle and, partly, in the liver." (PMID 34199514, 2021). "Insulin resistance (IR) is defined as a metabolic state in which the responsiveness of the target tissues to insulin concentrations is reduced, and IR plays a crucial role in various metabolic diseases." (PMID 33975592, 2021). "Type 2 diabetes mellitus (T2D) patients are the largest group of diabetic patients; this disease is characterized by hyperglycemia, insulin resistance, and impaired insulin secretion." (PMID 33800673, 2021). "Insulin sensitivity and insulin resistance are improved because HCQ can inhibit the degradation of insulin, reduce hyperglycemia associated inflammation and activate protein kinase β (Akt) resulting in increased glucose uptake and glycogen synthesis." (PMID 34360449, 2021). "Fasting blood glucose and fasting insulin levels declined, with improved insulin resistance after treatment in both groups." (PMID 33598383, 2021).